KRAS (KRas proto-oncogene, GTPase)
Diseases named in the same sentence as KRAS in open-access papers (continued):
Sharing a sentence is not in itself a finding about the gene and the disease.
tumor (continued). "The sensitivity, specificity and accuracy of the assay for detecting KRAS mutations in peripheral blood and tumour tissue samples were 61.5, 93.1 and 83.3%, respectively." (PMID 23226727, 2012). "Thirteen patients showed KRAS point mutations in primary tumour tissue samples, and among them 4 had a Gly12Val mutation, 3 had a Gly13Asp mutation, 3 had a Gly12Asp mutation, 2 had a Gly12Ser mutation and 1 had a Gly12Cys mutation." (PMID 23226727, 2012). "Copy number loss of the KRAS locus was observed in the tumour of 5 patients who were all good responders including patients with a KRAS mutation." (PMID 22804917, 2012). "Macrophages and IL1β inactivate GSK3β in both HCT116 and Hke-3 cells and, consistently, stabilize Snail independently of the presence kRas mutations in tumor cells." (PMID 23029025, 2012). "ASLNAqPCR quantification of the mutated to wild type allele ratio clearly indicated the presence of tumor cell subclones in 7 of the 16 discrepant KRAS results (cases 1, 8, 9, 10, 11, 12) and in 3 of the 5 discrepant BRAF results (cases 2, 3)." (PMID 22558339, 2012). "This tumor was found to harbor a KRAS codon 12 mutation, the GGT → GTT transversion, corresponding to the Gly → Val amino acid change." (PMID 22682753, 2012). "KRAS point mutations were detected in primary tumour tissue samples of 13 patients (31.0%) and in peripheral blood samples of 10 (23.8%)." (PMID 23226727, 2012). "The commercial and academic-based laboratories included in this study provide reliable test results for common mutations in the KRAS gene from samples with an adequate percentage of tumor cells." (PMID 22534075, 2012). "In conclusion, this analysis of the MACRO study highlights the prognostic role of tumour KRAS mutation status in patients receiving chemotherapy in combination with bevacizumab, which is consistent with some literature reports but not others." (PMID 23174912, 2012). "A difference between the expression of miR-143 in good versus poor responders was more obvious in mutated KRAS tumours." (PMID 22804917, 2012). "Tumoral and metastatic samples were screened for KRAS codon 12 and 13 and BRAF mutations by SNaPshot and/or direct sequencing." (PMID 23136868, 2012). "Despite this, our findings are likely to assist molecular biologists in making rational decisions when selecting a reliable, efficient, and cost-effective method for detecting KRAS mutations in heterogeneous clinical tumor samples." (PMID 22995035, 2012). "Whilst none of the three EGFR array peptides was found among phosphosubstrates distinguishing tumor KRAS/BRAF mutation status at group level, all of the three peptides representing ERBB2 and ERBB4 were among the discriminating substrates." (PMID 23226389, 2012). "BRAF binds to and is downstream from the main effectors of KRAS, whose activating mutations are believed to support the chaotic tumor vascularity, by up-regulating the transcription of several angiogenic inducers, including VEGF-A." (PMID 22846499, 2012). "In one pair the primary tumor and the metastasis each contained a different KRAS mutation (exon 1 G12V and G12R, respectively)." (PMID 22528563, 2012). "There are studies correlating the activation of mTOR with tumor progression and metastatic potential in KRAS-mutated NSCLC models." (PMID 24281308, 2012). "Increased expression of miR-200b that targets KRAS was associated with improved PFS in patients with a mutated KRAS tumour." (PMID 22804917, 2012). "KRAS mutation analysis of primary tumour tissue samples is performed since metastatic tissue is often not available." (PMID 23226727, 2012). "The use of tumour KRAS mutation status as a biomarker to identify which patients are most likely to respond to cetuximab-based CRT requires further, larger scale investigation." (PMID 23077464, 2012). "Surprisingly, increased expression of miR-143 resulted in a shorter PFS in patients with a mutated KRAS tumour (HR 1.59 (1.01-2.50); p = 0.04)." (PMID 22804917, 2012).
tumor (continued). "Expression of KRAS protein was associated with tumor stages and also occurred more frequently in ever-smokers (P = 0.002)." (PMID 22537942, 2012). "Tumour tissue from 32 patients was available for KRAS analysis and KRAS mutations were detected in the tumour tissue of 13 patients (40.6%)." (PMID 23077464, 2012). "In KRAS mutated tumours increased miR-200b and decreased miR-143 expression were associated with a good PFS." (PMID 22804917, 2012). "Some studies found a discordance of KRAS mutations in primary tumours and metastatic sites, with an overall discordance observed in 4–32% of patients." (PMID 23226727, 2012). "Patients with a tumour harbouring a KRAS codon 12 or 13 mutation are resistant to anti-EGFR therapy." (PMID 22804917, 2012). "Correlation of CBS methylation, KRAS mutation and tumor relapse/metastasis status in primary stage II CRC samples." (PMID 23152928, 2012). "Expression levels were correlated with CIN and with disease-free survival, correcting for microsatellite instability, BRAF/KRAS mutation status, Dukes stage, chemo/radiotherapy, age, gender and tumour location." (PMID 23154512, 2012). "Surprisingly a decreased expression of miR-143 was associated with improved PFS in patients with mutated KRAS tumours." (PMID 22804917, 2012). "It was recently suggested that amplification of ERBB2 comprises another resistance mechanism, and that acquired resistance is conferred by mutation of EGFR itself or results from expansion of tumor subclones with mutated or amplified KRAS." (PMID 23226389, 2012). "Both EGFR and KRAS mutations were found more often in ADC than in other tumor types and EGFR mutations were more common in females compared to males." (PMID 22528563, 2012). "Cellularity was also predicted for those tumours bearing heterozygous KRAS mutations after deep KRAS sequencing." (PMID 23049875, 2012). "In the present study, binary supervised classification analysis of the ex vivo-generated phosphopeptide profiles discriminated correctly between tumor KRAS/BRAF wild-type and mutated samples in two-thirds of cases." (PMID 23226389, 2012). "The TaqMelt PCR assay—the cobas® KRAS Mutation Test—designed to detect 19 mutations in codons 12, 13, and 61 was shown to be superior in samples with a low percentage of tumor cells." (PMID 22358180, 2012). "Our results indicate commercial and academic laboratories provide reliable results for the common KRAS gene mutations at codons 12 and 13 when an adequate percentage of tumor cells is present in the sample." (PMID 22534075, 2012). "Eight patients showed KRAS point mutations in both their primary tumour and blood samples, and we found a concordance of KRAS mutation status between blood and primary tumour tissue samples in all 8 patients." (PMID 23226727, 2012). "The results for long-term survival and for an analysis investigating the relationship between survival and patient and disease characteristics, including tumour KRAS mutation status, and surgery type, are presented." (PMID 23077464, 2012). "For cetuximab, KRAS mutational status should be considered and preferred only in patients with wild-type KRAS tumours." (PMID 22068817, 2012). "The KRAS mutations identified in three of our tumor samples (2.6%) were identical G12A substitutions, which is a well-characterized activating mutation." (PMID 22994622, 2012). "In the case presented here, however, the tumor carries both a KRAS activating mutation and complete inactivation of PTEN, supporting dual activation of both the MEK/ERK and the PI3K/AKT axes." (PMID 22762308, 2012). "Five genotyping methods for determining the status of mutation of KRAS were assessed using frozen tissue from primary NSCLC tumor specimens." (PMID 22995035, 2012). "Elevated expression of mir-200b was associated with a better PFS in patients with a mutated KRAS tumour (HR 0.56 (0.28-1.15); p = 0.10)." (PMID 22804917, 2012).
tumor (continued). "The high incidence of oncogenic KRAS activating mutations found in PDAC (90% of tumours) has been proposed as a contributing factor to the limited effects of EGFR targeting." (PMID 21792199, 2011). "Mutually exclusive somatic mutations in either KRAS or BRAF are often reported in LMP tumours and LGOSCs (30–50%), but rarely in HGOSCs (<12%)." (PMID 22163003, 2011). "We assessed the concordance in KRAS mutation status in primary tumours and their corresponding liver metastases in an adequately powered study of 305 CRC patients." (PMID 21364579, 2011). "We showed that tissue from the primary tumour can reliably be used for KRAS mutation testing in order to select patients for anti-EGFR therapy." (PMID 21364579, 2011). "The presence of the mutations in a restricted and well defined region of the gene and the occurrence of the mutations in an high percentage of tumor cells facilitates the detection of KRAS mutations in tumor tissues." (PMID 22216189, 2011). "Our data also shows that in cases of low cellularity in tumor cell block material, cytology smears are better than cell block for KRAS mutational analysis." (PMID 29147262, 2011). "Both primary tumours had the same KRAS mutation (Gly13Asp), while the liver metastasis had a different KRAS mutation (Gly12Ser)." (PMID 21364579, 2011). "In contrast to these data, others have reported a discordance of KRAS mutation status in primary tumours and metastatic sites, with an overall discordance observed in 4–32% of the patients." (PMID 21364579, 2011). "Identification of differential downstream effector proteins for wild-type and oncogenic KRAS in the future will help elucidating if the wild-type KRAS allele possesses any tumor-suppressive function." (PMID 22113502, 2011). "KRAS mutations were found in 20 (33.9%) out of 59 bioptic tumour samples obtained before preoperative treatment." (PMID 21880132, 2011). "Other studies found that KRAS WT was associated with improved survival, or trended to tumor downstaging or response, while another study found associations between KRAS mutation with earlier stage and better survival." (PMID 21910869, 2011). "Among the 160 samples, one primary tumor and seven metastases were identified with KRAS mutations and 21 primary tumors and 26 metastases were found to have EGFR mutations." (PMID 21414214, 2011). "In this largest and most homogenous study to date, we conclude that both primary tumours and liver metastases can be used for KRAS mutation analysis." (PMID 21364579, 2011). "Comparison of cytology smears with resected tumor specimen showed that 89% (8 out of 9) were in agreement for KRAS mutational analysis." (PMID 29147262, 2011). "While the small number of recurrences and deaths due to NSCLC in our tumour-set makes it difficult to draw strong conclusions, transcriptional profiles linked to tumour recurrence suggest KRAS pathway activation." (PMID 21385341, 2011). "Tumours with any variation in codons 12, 13 or 61 of KRAS and in exon 15 of BRAF were classified as mutated." (PMID 21901162, 2011). "The other patient showed two different KRAS mutations within the same tumour, of which one is concordant with the liver metastasis." (PMID 21364579, 2011). "The COLD-PCR assay used in this study detected EGFR and KRAS mutations present in tumour DNA comprising as little as 5–10% of total sample DNA." (PMID 21949883, 2011). "This is the first adequately powered study in CRC that compares KRAS mutation status between primary tumours and their corresponding liver metastases." (PMID 21364579, 2011). "We analyzed the frequencies of specific KRAS mutations in different disease types, with mutations identified in at least 5 tumor samples." (PMID 21829508, 2011).
tumor (continued). "Five patients (1.6%) harboured different KRAS mutation types in the primary tumour compared with the metastases." (PMID 21364579, 2011). "There is a very high concordance of KRAS mutational status between the primary tumor and metastasis, ranging from 92–100%." (PMID 21437184, 2011). "When only KRAS WT cases were analyzed patients whose tumours carried the BRAF mutation had even more significantly lower TTP and OS (TTP: 2.1 vs. 6.4 months, p<0.0001; OS: 4.3 vs. 16.3 months, p <0.0001) compared with the results in the whole population." (PMID 21283802, 2011). "In 294 patients (96.4% 95% CI 93.6–98.2%), the same KRAS mutation status was obtained from the primary tumour and the corresponding liver metastasis." (PMID 21364579, 2011). "Of the 1,125 patients enrolled, 395 had tumor samples available and KRAS mutation was detected in 19%." (PMID 21444946, 2011). "Following the discovery of KRAS mutations in association with anti-EGFR moAbs resistance, the KRAS mutational characterization of mCRC tumours is, currently, preformed in routine basis before any treatment decision." (PMID 21283802, 2011). "First, the HE coupes of all patients with a discordant KRAS mutation status between the primary tumour and liver metastasis were revised." (PMID 21364579, 2011). "Tumours possessing mutations of KRAS express genes playing key roles in cell growth, chromosome organisation and gene regulation." (PMID 21385341, 2011). "Only one patient had a wild-type status of the primary tumour, while the metastasis showed a KRAS mutation." (PMID 21364579, 2011). "In the case of cetuximab, results of a retrospective analysis of KRAS mutational status in tumour biopsy samples of patients included in several randomised phase III clinical trials have confirmed that KRAS is a solid biomarker of resistance to cetuximab." (PMID 20234366, 2010). "Misclassification of KRAS mutation status has important clinical consequences because KRAS testing of tumor tissue is often used as the sole determinant for selection of anti-EGFR therapy." (PMID 21110880, 2010). "This cooperative nature between Apc and KRAS mutations in leading to increased tumor formation is similar to that observed in two previous studies, one involving Apc+/1638/KRASV12 double transgenic mice and the other ApcMin/K-rasD12 double transgenic mice." (PMID 20298593, 2010). "We confirmed that both regular-PCR melting curve analysis and Sanger sequencing detected a KRAS mutation (G12D) when DNA was prepared with morphology-guided dissection to enrich for tumor cells in our standard fashion." (PMID 21110880, 2010). "From the data presented here, we suggest that in sporadic cancer, a single LKB1 mutation or down-regulation of protein expression would be sufficient to synergize with KRAS mutation to drive tumor progression." (PMID 20452353, 2010). "One of them is that KRAS mutations should be examined in the clinical trials on the effect of EGFR blockade in this tumor type." (PMID 20565817, 2010). "Nevertheless, these findings indicate a critical role for wild-type KRAS alleles in hypoxia and provide a potential explanation for the aggressive behavior of tumor cells that can survive in the hypoxic microenvironment." (PMID 20532039, 2010). "In consideration of an inhomogeneous genotype concerning the KRAS mutation status of the tumor cells, more sensitive detection methods are required." (PMID 21197450, 2010). "Cancer tissue presents challenges for KRAS mutation analysis because each specimen is a unique mixture of tumor and non-tumor cells." (PMID 21110880, 2010).
tumor (continued). "Tumor and normal tissues from 69 patients were screened for KRAS mutations and genotyped for FcgammaRIIa and FcgammaRIIIa polymorphisms." (PMID 20680105, 2010). "In the era of targeted therapy for cancer, molecular diagnosis of particular genetic markers in tumours enables a more individualised treatment of patients, as was recently shown for KRAS mutation status and response rate to anti-EGFR therapy in CRC." (PMID 20959826, 2010). "Both assays have a sufficient analytical sensitivity to efficiently detect KRAS mutations even in samples with < 10% tumor cells." (PMID 21122130, 2010). "Tumour specimens from 48 metastatic CRC patients treated with cetuximab-based chemotherapy were evaluated for KRAS and BRAF mutational status and MKP-1 expression as assessed by immunohistochemistry." (PMID 20234366, 2010). "PCR methods are used to detect the most common mutations in codons 12, 13, and 61 of the KRAS gene in formalin fixed paraffin-embedded or frozen tumor tissue." (PMID 20877448, 2010). "In the overall study population, the presence of a KRAS mutation was significantly associated with proximal location of the tumours (P=0.05)." (PMID 20959826, 2010). "Our diagnostic algorithm for KRAS analysis includes reanalysis of all samples with < 10% tumor cells using an independent assay." (PMID 21122130, 2010). "Accelerated CRC tumor progression due to KRAS mutation was also induced in LDM CTX treated xenografts despite a significant anti-angiogenic effect." (PMID 21159176, 2010). "As inappropriate Ras activation is known to promote tumor cell proliferation we examined the four cell lines for KRAS gene mutations." (PMID 20565817, 2010). "Mutations in BRAF (P=0.002) and KRAS (P=0.054) occurred more frequently in patients with diffuse TOPK staining compared with patients with wild-type tumours." (PMID 19935791, 2010). "The frequency of tumor mutations in either KRAS or BRAF increased with patient age, both when comparing age groups and with age as a continuous variable." (PMID 21103049, 2010). "KRAS mutational status was available in 42 of these patients and 13 (31%) of them carried a mutation in their primary tumours." (PMID 20485284, 2010). "The frequency of KRAS mutation (20/40 as assessed by the Amgen laboratory) in the tumor biopsy specimens used in this study is consistent with that previously observed in clinical studies investigating KRAS mutations in CRC." (PMID 20398393, 2010). "In a large series of >800 samples tested for KRAS, using a highly sensitive SNaPshot-based method, we observed a discordant KRAS mutational status between tumours and metastases in 10% of the paired samples." (PMID 21139621, 2010). "We sought to elucidate the correlation between KRAS mutational status, clinicopathologic factors, prognosis, metastasis pattern and concordance between the primary tumor and matched metastases in patients with metastatic CRC." (PMID 20020061, 2009). "The tumor was found to harbor two KRAS mutations, Gly12Asp (ΔCT value 6.9, cutoff 8) and Gly13Asp (ΔCT value 5.6, cutoff 9)." (PMID 19832985, 2009). "In these patients, KRAS mutational status in the primary tumor was previously analysed for clinical purposes prior to cetuximab administration." (PMID 20020061, 2009). "KRAS mutation analysis was performed tested in tumor samples collectedfrom over 1000 participants of the “CRYSTAL”, “OPUS”, NCIC-CO.17 trial and panitumumab trials." (PMID 19365583, 2009). "Three RAS genes produce four Ras proteins, KraS 4A, KraS 4B, H-Ras, and N-Ras, that are more than 90% homologous but demonstrate a high degree of tumor-type mutation specificity." (PMID 19636423, 2009). "MASI in its various forms is frequently present in mutant EGFR and KRAS tumor cells, and is associated with increased mutant allele transcription and gene activity." (PMID 19826477, 2009).